IGF1R (insulin like growth factor 1 receptor)
Diseases named in the same sentence as IGF1R in open-access papers (continued):
Sharing a sentence is not in itself a finding about the gene and the disease.
colorectal cancer (continued). "One of the major pathways involved in colorectal cancer development and progression is IGF-1R." (PMID 30987250, 2019). "Thus, targeting the IGF-1R/IGF-1 signaling pathway can be considered as an effective approach to both colorectal cancer prevention and treatment." (PMID 30987250, 2019). "MiR-143-3p has been shown to target KRAS and IGF1R in colorectal cancer." (PMID 29137392, 2017). "MiR-145-5p is also known to target IGF1R in colorectal cancer, as well as EGFR in LAC." (PMID 29137392, 2017). "In addition, activated c-Met and IGF-1R have been reported to drive PI3 kinase signaling in colorectal cancers." (PMID 27840833, 2016). "The IGF‐1R is expressed in both normal colonic mucosa and human colorectal cancers." (PMID 27734632, 2016). "Expression of IGF1R is up-regulated in CSCs in human colorectal cancer." (PMID 27813496, 2016). "Overall, we believe that our novel findings on regulation of the MIB pathway by IGF-1R provide a platform for immediately testable hypotheses of high translational relevance for the treatment of colorectal cancer in particular and cancer in general." (PMID 25895029, 2015). "The efficacy and safety of anti-IGF1R antibodies have been explored in a wide variety of malignancies including bone and soft tissue sarcomas, squamous cell carcinoma, pancreatic cancer, lymphomas, colorectal cancer, and non-small cell lung cancer (NSCLC)." (PMID 25170759, 2014). "Our objective was to assess tumor uptake of fluorodeoxyglucose by positron-emission tomography in patients with chemotherapy-refractory colorectal cancer treated with an anti-insulin-like growth factor receptor type 1 (anti-IGF-1R) monoclonal antibody, robatumumab." (PMID 24905030, 2014). "Finally, we showed that miR-143/145 inhibited IGF1R expression and consequently suppressed the proliferation of colorectal cancer cells invitro." (PMID 25474488, 2014). "We next investigated whether miR-143/145 levels were inversely correlated with IGF1R protein expression in colorectal cancer tissues." (PMID 25474488, 2014). "Furthermore, we showed that miR-143/145 can inhibit IGF1R expression to suppress the proliferation of colorectal cancer cells." (PMID 25474488, 2014). "In summary, the findings in this study and other recently completed studies suggest that monoclonal antibodies directed against IGF-1R may have little utility as a treatment for colorectal cancer in unselected patient populations." (PMID 24905030, 2014). "Similarly, the expression of IGF1R mRNA was found to be down-regulated in peripheral blood cells and stimulated monocytes from patients with advanced stages of colorectal carcinoma (CRC)." (PMID 25403427, 2014). "Recent studies have provided several lines of evidence indicating that targeting of IGF-1R may as serve as the basis for clinical treatment of colorectal carcinoma." (PMID 24182354, 2013). "Previous studies have reported that the level of IGF1R itself may have predictive value in breast, lung, and colorectal cancers." (PMID 22438913, 2012). "■Quinoline;■Investigational for Ewing sarcoma (phase 2), colorectal carcinoma (phase 1), head and neck malignant neoplasia (phase 2), hepatocellular carcinoma (phase 2), and ovarian cancer (phase 1);■Insulin-like growth factor 1 receptor (IGF-1R) and insulin receptor inhibitor." (PMID 40298549, 2025). "Monensin could suppressed IGF1R expression via increasing IGF1 in colorectal cancer cells." (PMID 36896461, 2023). "Notably, another recent report suggested that chemoresistance of colorectal cancer cells to the DNA replication inhibitor 5-fluorouracil results from a potent cell survival mechanism based on sustained translation of IGF-1R mRNA and impaired ribosomal function." (PMID 36017326, 2022). "Furthermore, it has been revealed that circ_0067835 knockdown could suppress cell progression and enhance cell radiosensitivity of colorectal cancer partially by sponging with miR-296-5p/IGF1R axis." (PMID 36262967, 2022).
colorectal cancer (continued). "Additionally, Let-7e was showed to be able to control IGF1 R expression in colorectal cancer cells suggesting that Let-7e could be used in IGF1 R-targeted therapeutics in anticancer therapy." (PMID 32752917, 2020). "Overall, our in vitro and in vivo data confirmed the anti-cancer activity of curcumol, which was related to a significant inhibition of IGF-1R and activation of p38 MAPKs, indicating that curcumol may be a potential anti-tumor agent for colorectal carcinoma therapy." (PMID 26307972, 2015). "However, the role of IGF1R in colorectal cancer remains to be elucidated." (PMID 25474488, 2014). "However, very little is known about the regulation of IGF1R expression in colorectal cancer." (PMID 25474488, 2014). "Thus, IGF1R offers a particularly promising molecular target for colorectal cancer therapy." (PMID 25474488, 2014). "In colorectal cancer (CRC), PYCR1 is phosphorylated at Tyr‐135 by nuclear IGF1R under hypoxia, which promotes its binding to ELK4 and recruitment to gene promoters." (PMID 39422696, 2024). "For therapeutic intervention, colorectal cancer organoid and in vivo studies demonstrated the benefit of co-targeting IGF1R and YAP1 with the anti-IGF1R tyrosine kinase inhibitor (TKI) picropodophyllin (PPP) and verteporfin (VP), a YAP1 inhibitor." (PMID 38892104, 2024). "It has been showed that IGF1R plays a key role in the colorectal cancer and PI3K/Akt as well as Ras/Raf/MEK/ERK pathways are the downstream mediators of the IGF1R signaling in cancers." (PMID 36896461, 2023). "Based on TCGA database analysis, We discovered that the expressions of IGF-1, IGF1R and RAGE in colorectal cancer tissues were different from those in normal tissues." (PMID 36890832, 2023). "We found that the expressions of IGF-1, IGF1R and RAGE in colorectal cancer tissues were different from those in normal tissues." (PMID 36890832, 2023). "Here, the authors show nuclear localized PYCR1 undergoes IGF1R-mediated phosphorylation under hypoxia, binds with ELK4 and recruits SIRT7 to modulate transcription of target genes to promote colorectal cancer progression." (PMID 37777542, 2023). "Although both IGF-1R and Livin are potential biomarkers for CRC, only a few studies have investigated their role in normal mucosa-colorectal adenoma-colorectal cancer progression." (PMID 35931997, 2022). "In colorectal cancer (CRC), IGF1R gene and protein expression levels are usually elevated in cancerous tissues as compared to adjacent normal tissues." (PMID 35651701, 2022). "In colorectal cancer, the molecule network IGF1-HOXA13-ACLY/IGF1R and CXCL12-HOXB5-CXCR4/ITGB3, targeted blocking the downstream protein with small molecular compounds serves as a promising anticancer therapy." (PMID 34722321, 2021). "Therefore, inhibiting IGF1R may be an effective method for the treatment of colorectal cancer." (PMID 33688358, 2021). "In colorectal cancer, HOXA13 overexpression mediated by insulin-like growth factor 1 promotes metastasis through upregulating downstream targets ATP-citrate lyase and insulin-like growth factor 1 receptor." (PMID 34722321, 2021). "In this regard, luteolin was already reported to alter antioxidant activity, modulate the MAPK and p-IGF-1R/PI3K/AKT/mTOR signaling pathways, and induce mitochondrial dysfunction in GBM, colorectal cancers and other malignancies." (PMID 33291443, 2020). "Our data suggest that the treatment of colon tumor cells with IGF-1R inhibitors stimulates p70S6K1 activity via MEK1/2 to promote survival, providing a new strategy for colorectal cancer therapeutics." (PMID 32843616, 2020). "The IGF1R mAbs will not prevent signalling via IGF2 binding to the INSR‐A receptor, which would be another route to evade IGF1R inhibition; indeed, increased phospho‐INSR levels have been observed in response to an EGFR inhibitor in colorectal cancer cells." (PMID 31179642, 2019).
colorectal cancer (continued). "For example, curcumin has been shown to downregulate IGF-1R and INSR in colorectal cancer cells, and to block IGF-induced activation of IGF-1R, PI3K-AKT and mTOR, suppressing carcinogen-driven skin tumorigenesis in an Igf-1 driven model." (PMID 31416218, 2019). "It is worth mentioning that in colorectal cancer cell lines IGF2 overexpression regulates sensitivity and/or response to IR/IGF1R TKI." (PMID 31480557, 2019). "We observed a co-upregulation of the insulin-like growth factor receptor (IGF-1R)/AKT/mammalian target of rapamycin (mTOR) [InAT] axis and the mevalonate-isoprenoid biosynthesis (MIB) pathways in colorectal cancer stem cells (CSCs) in an unbiased approach." (PMID 25895029, 2015). "Emerging literature highlights the role of Insulin-like growth factor (IGF)-1 receptor (IGF-1R) pathway in regulating ‘CSC properties’ in several epithelial cancers, including colorectal cancer." (PMID 25895029, 2015). "By overexpressing miR-143/145 in Caco2, HT29 and SW480 colorectal cancer cells, we experimentally validated that miR-143/145 directly recognizes the 3′-UTR of the IGF1R transcript and regulates IGF1R expression." (PMID 25474488, 2014). "After examining a panel of colorectal carcinoma cell lines and xenografts, we have found that the cell lines respond differently to the treatment of PPP, an IGF-1R inhibitor." (PMID 24182354, 2013). "Examination of colorectal carcinomas has revealed elevation of the transcripts of IGF-I/II and IGF-1R." (PMID 24182354, 2013). "We examined the IGF-1R downstream AKT and ERK growth pathways and BAD-mediated mitochondrial apoptotic pathway in PPP-treated colorectal carcinoma cells." (PMID 24182354, 2013). "A phase II trial, however, has concluded that the IGF-1R neutralizing antibody IMC-A12, alone or in combination with the EGFR antibody cetuximab, is insufficient for the treatment of colorectal carcinomas." (PMID 24182354, 2013). "In this study, we demonstrate a significant overexpression of IGF-1R, IGF-2 and MMP-7 mRNA in colorectal cancer tissues." (PMID 22159423, 2012). "Also, the expression of IGF-1R and Livin genes was increased in the 275 CRC cases from the GEPIA2 dataset and 286 colorectal cancer cases from the UALCAN portal dataset." (PMID 35931997, 2022). "But the expression of IGF1R, IGF2R, and PPARG was negatively correlated with the number of infiltrated CD8+ T cells in colorectal cancer; the related antidiabetic drugs may produce negative effect on anti-PD1 tumor inhibition." (PMID 36033393, 2022). "Interestingly, PI3K activation in KRAS-mutant lung and colon cells is dependent on insulin-like growth factor 1 receptor (IGF1R) activity and a combination of MEK and IGF1R inhibitors showed synergistic effects both in NSCLC and colorectal cancer (CRC)." (PMID 34200676, 2021). "By binding with IGF-1, IGF-2, and insulin, IGF-1R activates downstream pathways including phosphoinositide 3 kinase (PI3K)/AKT and Ras/extracellular signal-regulated protein kinase (ERK) pathways, two frequently activated pathways in colorectal cancer." (PMID 32843616, 2020). "Further, IFITM2 was significantly up-regulated and induced after activation of beta-catenin signaling in colorectal cancers, and it was also reported to promote gastric cancer growth and metastasis through the insulin-like growth factor (IGF1)/IGF1 receptor (IGF1R)/STAT3 signaling pathway." (PMID 32765489, 2020). "A significant negative correlation between IGF1R protein and miR-378a-3p expression levels was observed in colorectal cancer tissues." (PMID 26255816, 2015).
colorectal cancer (continued). "After measuring the expression levels of miR-143/145 and IGF1R in human colorectal cancer tissue and paired noncancerous tissue, we detected an inverse correlation between miR-143/145 levels and IGF1R protein levels." (PMID 25474488, 2014). "In colorectal cancer, studies with NVP-AEW541 suggested that a combination therapy targeting both EGFR and IGF-1R could be a promising approach." (PMID 23525758, 2013). "In addition, IGF-1R activates the extracellular signal-regulated kinase (ERK) and nuclear factor-κB (NF-κB) pathway that protect colorectal carcinoma cells from tumor necrosis factor-α (TNFα) induced apoptosis." (PMID 24182354, 2013). "Furthermore, colorectal carcinomas express high levels of IGF-I/IGF-II, IGF-1R mRNA, and IGF-1R protein, as shown in this study." (PMID 24182354, 2013). "Therefore, in parallel to analyses of IGF-1R, IGF-1/2 and MMP-7 mRNA expression in tissue from colorectal cancer patients, we assessed the effects of the IGF-1R-inhibitory compound PPP in four colon carcinoma cell lines." (PMID 22159423, 2012). "In colorectal cancer, IGF1 stimulation activates the IGF1R/AKT pathway and induces the transcriptional activation and expression of the transcription factor HOXA13, thereby promoting the in vitro migratory and invasive abilities of colorectal cancer cells and in vivo metastases formation." (PMID 38892104, 2024). "Programmed cell death 4 (PDCD4) was reported to downregulate p70S6K1 phosphorylation and translation, but not p70S6K2, leading to chemosensitivity of colorectal cancer (CRC) cells to the insulin-like growth factor 1 receptor (IGF1R) inhibitor linsitinib (OSI-906)." (PMID 35008473, 2021). "Finally, in a randomized phase II trial of IMC-A12 used alone or in combination with cetuximab in patients with advanced colorectal cancer, none of the twenty-three patients treated with the single-agent IGF-1R antibody responded." (PMID 24212944, 2011). "For example, in colorectal cancer, IGF-1R signaling enriches the side-population cell (cells that are best at effluxing the dyes and have been referred to as CSCs) but not the non-side-population cells, indicating the role of IGF-1R in CSC features." (PMID 33511137, 2020).
melanoma (150 papers, 2008 to 2025). A malignant, usually aggressive tumor composed of atypical, neoplastic melanocytes. "The levels of miR-99a/-100 are significantly higher in nevi than in malignant lesions and are negatively associated with IGF1R expression; restoration of miR-99a/-100 reduces IGF1R expression and melanoma cell proliferation." (PMID 40161350, 2025). "Next, we performed tumor heterotopic transplantation and pulmonary metastases in IGF1R-deficient mice using melanoma and Lewis lung carcinoma (LLC) cells." (PMID 35688943, 2022). "As a complement to the LLC experimental pulmonary metastasis model, we generated an additional mouse model: B16-F10 (melanoma) cells were intravenously injected in IGF1R-deficient (CreERT2) and Igf1rfl/fl mice to induce lung metastasis." (PMID 35688943, 2022). "We next examined that survival curves of melanoma patients from the TCGA data set for patients with a BRAF mutation along with high or low levels of INSR or IGF1R." (PMID 34831014, 2021). "In contrast, expressed PTEN regulates IGF1R-mediated BRAF inhibitor resistance in some melanoma, while melanoma with PTEN loss decreased IGF1R56." (PMID 34282258, 2021). "In contrast, the A alleles in IGF1R SNP rs2229765 presented a protective effect on melanoma in the current study." (PMID 32150843, 2020). "Lastly, the GEM cohort was stratified by gender and logistic regression analyses were performed to measure the associations of rs1520220/IGF1 and rs2229765/IGF1R and melanoma risk in men and women, respectively." (PMID 32150843, 2020). "The IGF1 rs1520220 and IGF1R rs2229765 SNPs were thus further analyzed in the logistic regression models to determine the odds ratio (OR) of melanoma in individuals carrying minor alleles/genotypes in comparison with the reference alleles/genotypes." (PMID 32150843, 2020). "The rs1520220 in IGF1 and rs2229765 in IGF1R variants were significantly associated with melanoma risk in the GEM dataset after Benjamini-Hochberg multiple comparison correction, although they were not validated in the GENEVA set." (PMID 32150843, 2020). "In an attempt to understand the genetic predisposition to the gender-biased risk of cutaneous melanoma, a gene prioritization approach and case-control study design were used to measure melanoma associations with a group of 13 SNPs from the ER/IGF1R pathway." (PMID 32150843, 2020). "It was found that overexpression of IGF-1R was significantly linked to gain of a metastatic phenotype in synovial sarcoma, melanoma, and gastric cancer." (PMID 32477459, 2020). "Most importantly, using animal models, we demonstrated that IGF-1R inhibition not only caused complete regression of melanoma xenografts but also drastically reduced the incidence of liver metastasis in vivo." (PMID 29946532, 2018). "Targeting of the IGF1R pathway exerts potent anticancer effects and combined inhibition of MAPK, PI3K, and IGF1R successfully inhibited melanoma growth and overcame resistance of melanoma cells harboring BRAF and PTEN mutations." (PMID 28417283, 2017). "Because increased CRAF and IGF1R activity have each been implicated in melanoma BRAFV600E inhibitor resistance, we examined RGC vs. corresponding TNPC for phospho- CRAF and IGF1R levels by immunoblotting." (PMID 27611946, 2017). "Epidemiological evidence suggests that high levels of circulating IGF-1 and IGF-1R expression are associated with a higher risk of several common cancers, including melanoma." (PMID 27764776, 2016). "MAPK/Erk1/2 activation via C-RAF overexpression and upregulation of RTKs (PDGFRβ and IGF-1R) or N-RAS mutation have been reported to be among the mechanisms by which melanoma cells acquire resistance to B-RAF inhibitors." (PMID 23418523, 2013). "IGF1R has already been implicated in melanoma almost 20 years ago, and data concerning its exact role in the pathogenesis of this disease is rapidly accumulating." (PMID 22747855, 2012).